GIP (gastric inhibitory polypeptide)
Description:
Potent stimulator of insulin secretion and relatively poor inhibitor of gastric acid secretion.
Tractability: Small molecule: a structure with a bound ligand is known. Antibody: its Gene Ontology location is reachable by antibodies, with high confidence; UniProt places it where antibodies can reach, with medium confidence; UniProt predicts a signal peptide or a membrane-spanning region.
Gene: Protein-coding gene on chromosome 17 (48,958,554 to 48,968,596, reverse strand). Ensembl gene ENSG00000159224.
Subcellular location: Secreted
Pathways (Reactome):
Signal Transduction: G alpha (s) signalling events; Glucagon-type ligand receptors
Metabolism of proteins: Synthesis, secretion, and inactivation of Glucose-dependent Insulinotropic Polypeptide (GIP)
Gene Ontology:
Molecular function: gastric inhibitory polypeptide receptor binding; protein binding; glucagon receptor binding; hormone activity; receptor ligand activity; signaling receptor binding
Biological process: adenylate cyclase-activating G protein-coupled receptor signaling pathway; gastric inhibitory peptide signaling pathway; regulation of insulin secretion; response to starvation; signal transduction; regulation of fatty acid biosynthetic process; response to glucose
Cellular component: endoplasmic reticulum lumen; extracellular region; secretory granule lumen
Genetic constraint (gnomAD): Loss-of-function variants: 12 observed, 13.11 expected, observed/expected ratio (o/e) 0.92, 90% interval 0.58 to 1.48. The upper end of that interval is the gene's LOEUF score, 1.48, which puts it in group 6 of 6, group 1 being the genes least tolerant of losing a copy. Missense variants: 165 observed, 158.77 expected, observed/expected ratio (o/e) 1.04, 90% interval 0.92 to 1.18. Synonymous variants: 66 observed, 66.77 expected, observed/expected ratio (o/e) 0.99, 90% interval 0.81 to 1.21.
Homologues: Orthologues: chimpanzee GIP (99% identical), macaque GIP (96% identical), pig GIP (71% identical), rat Gip (71% identical), mouse Gip (69% identical), rabbit GIP (69% identical), dog GIP (61% identical), guinea pig GIP (55% identical), tropical clawed frog gip (26% identical), zebrafish gip (18% identical).
Diseases named in the same sentence as GIP in open-access papers:
GIP is named in the same sentence as 205 diseases in open-access papers, as found by Europe PMC text mining. Sharing a sentence is not in itself a finding about the gene and the disease. The quoted sentences say what the papers report.
Obesity (438 papers, 2008 to 2026). Accumulation of substantial excess body fat. "It is reported that elevated fasting plasma GIP levels in obesity are associated with increased production of pro-inflammatory cytokines, adipocyte lipid deposition, and visceral abdominal fat." (PMID 41528263, 2026). "Although the exact mechanism underlying the anti-obesity effect of GIP or the GIPR system is unclear, cumulative results support that the therapeutic effect associated with the modulation of the GIP system is mediated by the central nervous system (CNS)." (PMID 39940910, 2025). "Retatrutide: A triple receptor agonist targeting GLP-1, GIP, and glucagon receptors, retatrutide has demonstrated safety in phase II trials involving patients with obesity and metabolic dysfunction-associated steatotic liver disease (MASLD)." (PMID 40282969, 2025). "A genome‐wide association study (GWAS) has identified that variations in genes related to the GIP signaling pathway are associated with obesity." (PMID 39540705, 2025). "Based on this evidence, GIP is considered an obesity hormone, and GIP deficiency is believed to protect mice from diet-induced obesity." (PMID 39940910, 2025). "Triple agonists like retatrutide—targeting GLP-1, GIP, and glucagon receptors—have achieved up to 24.2% weight loss in adults (12-mg group), signaling a new generation of anti-obesity pharmacotherapy." (PMID 41300545, 2025). "Elevated GIP levels, particularly in obesity, are associated with increased hepatic fat accumulation, elevated markers of liver injury, and increased plasma levels of fibroblast growth factor 21 (FGF-21), a marker of metabolic stress." (PMID 41465555, 2025). "Regarding the interaction of GIP and insulin, even though higher GIP levels are shown to increase insulin secretion and promote satiety, many studies associate GIP levels with obesity." (PMID 40362890, 2025). "A chronic increase in GIP levels in GIP transgenic mice was associated with reduced diet-induced obesity." (PMID 39940910, 2025). "Deletion of GIP receptor has been found to counteract high-fat diet induced weight gain in mice, suggesting a causal role of GIP in development of obesity." (PMID 38831203, 2024). "In 2022, a modified version of the GLP-1/GIP dual agonist, tirzepatide (Zepbound®), developed by Eli Lilly induced an average weight loss of 21% in humans with obesity and 15% weight loss in obese patients with diabetes." (PMID 39297680, 2024). "Obesity is associated with increased GIP levels and K-cell hyperplasia because fat is a potent stimulant of GIP release." (PMID 38255264, 2024). "Obesity associated hypersecretion of GIP is only seen in response to much bigger meals than were used in our study." (PMID 38490484, 2024). "GIP, also known as gastric inhibitory polypeptide, is a biomarker associated with metabolic disorders, including type 2 diabetes and obesity." (PMID 38255264, 2024). "These hormones exhibit a wide range of antidiabetic actions, but interestingly, ablation of GIP action has been linked to amelioration of spontaneous and diet-induced obesity in rodents." (PMID 37228045, 2023). "Multiple approved glucagon-like peptide 1 (GLP1) and gastric inhibitory polypeptide (GIP) agonists (alone or in combinations) induce highly significant weight loss in persons with obesity." (PMID 38048365, 2023). "Alterations in gut hormone secretion have been associated with the pathogenesis of obesity, and attenuated responses of GIP, GLP-1, and PYY have been reported both in humans and in rodent models." (PMID 35600607, 2022). "Our previously published data show an association of high GIP levels in obese subjects with elevated liver enzymes, accompanied by an altered miRNA profile characteristic of hepatic and lipid complications of obesity." (PMID 36010335, 2022).
Obesity (continued). "Since endocrinological changes such as changes to leptin, ghrelin, and GIP levels that promote weight regain persist long after weight loss, patients with obesity regain weight after one year of lifestyle modification." (PMID 36068534, 2022). "Excess fat and carbohydrate intake is also well known to cause obesity concomitant with hyperinsulinemia and hyper‐GIP secretion in mice and humans." (PMID 35452190, 2022). "By contrast, overexpression of GIP in mice also led to decreased energy intake and reduced weight gain associated with diet-induced obesity." (PMID 33803183, 2021). "The efficacy of GLP-1 RAs and DPP-4 inhibitors in normalizing glucose metabolism indicates the possibility of GLP-1 and GIP deficiencies under conditions of obesity and/or glucose intolerance." (PMID 34205659, 2021). "Overall, in the current study, we indicate that exaggerated fasting and postprandial GIP secretion in obesity is associated with elevated ALT, GGT, FLI, as well as FGF-21 plasma levels." (PMID 32069846, 2020). "Exaggerated fasting and postprandial secretion of GIP in obesity are associated with elevated liver damage markers as well as FGF-21 plasma levels." (PMID 32069846, 2020). "Selected studies indicate that disturbed GIP signaling in obesity as well as in diabetes is associated with impairment of fat metabolism and liver fat accumulation, but the mechanisms are still poorly understood." (PMID 32069846, 2020). "We therefore evaluated GIP secretion in leptin-deficient Lepob/ob mice, which develop severe obesity under the normal chow diet." (PMID 31509948, 2019). "Nonetheless, the GIP variants directly linked to obesity or insulin dysfunction are less well characterized." (PMID 28530680, 2017). "Moreover, GIP confers protection against bone deterioration in multiple pathological conditions, including postmenopausal osteoporosis, inflammatory bone loss, obesity, and diabetes, etc., suggesting therapeutic potential beyond physiological contexts." (PMID 41596254, 2026). "The introduction of glucagon-like peptide-1 receptor agonists (GLP-1 RAs) and dual incretin agonists targeting both the GIP and GLP-1 receptors (GIP/GLP-1 dual agonists) has reshaped obesity management, approaching degrees of weight loss previously achievable largely through metabolic surgery." (PMID 41909366, 2026). "Literature suggests that obesity may be associated with GIP hypersecretion as a compensatory mechanism in IR, potentially indicating incretin resistance." (PMID 40806228, 2025). "Further studies are needed to establish the optimal modulation of GIP receptors for the management of obesity and associated metabolic disorders, as well as to establish the indications and limitations of the GIP-targeting molecules for the pediatric population." (PMID 40649920, 2025). "Incretin-based therapies, such as glucagon-like peptide 1 receptor agonists (GLP-1 RAs) and dual glucose-dependent insulinotropic polypeptide/glucagon-like peptide 1 receptor agonists (GIP/GLP-1 RAs) have emerged as transformative treatments for managing obesity and cardiometabolic risk." (PMID 39852297, 2025). "Reduced sensitivity to GLP-1 and GIP in adipose precursor cells and in mature fat cells in obesity-associated insulin-resistant states indicates a “GLP-1/GIP-resistant” phenotype as a potential genetic predisposing factor for the development of clinical glucose intolerance and IR." (PMID 39201336, 2024). "In general, obesity is associated with marked increases in plasma GIP levels." (PMID 39436694, 2024). "Data in the literature support the hypothesis that GIP promotes fat deposition, and in vitro experiments on GIP-R-deficient show a resistance to obesity." (PMID 38978621, 2024). "The current data may help inform future studies that examine the efficacy of GIP-based therapies in the reduction of clinical adverse effects associated with IBD in patients living with T2D or obesity." (PMID 39723966, 2024).
Obesity (continued). "The mechanism underlying associations of GIP with lipid metabolism warrants further study, especially in the light of the development of new incretin-based pharmacotherapies for the treatment of obesity, dual GIP and GLP-1 receptor agonists." (PMID 36010335, 2022). "Therefore, both the blockade of endogenous GIP signaling and exogenous enhanced GIP agonism reduced bodyweight by decreasing food intake, which is partly controversial in regard to the well‐characterized association of GIP with fat‐induced obesity." (PMID 35452190, 2022). "The synergistic actions of glucagon to reduce food intake and increase energy expenditure, GLP‐1 to reduce calorie intake, and GIP to potentiate bodyweight loss may aid in the treatment of obesity." (PMID 34713962, 2022). "Since GIP has been shown linked to nutrient absorption, it is likely that GIP may also contribute to the onset of obesity and its comorbidities such as diabetes." (PMID 35224107, 2022). "However, with a proposed role for GIP in development of obesity coupled with a loss of insulinotropic effect in T2DM, therapeutic application did not follow such a straightforward path." (PMID 34093449, 2021). "Further research should focus on the effects of isomaltulose ingestion on concentrations of glucose, insulin and GIP during exercise in clinical populations, such as diabetes or obesity, as there is often a higher hypoglaemic risk during exercise following a meal." (PMID 34001166, 2021). "The risk increase for death may, as an example, be mediated by unhealthy fat distribution, independent of insulin levels, that is associated with higher GIP release, or by promotion of obesity." (PMID 31974732, 2020). "Excessive secretion of GIP leads to the deposition of lipids in peripheral tissues (liver, muscle, etc.)and islet β cells, which causes impaired insulin resistance and secretory function, while inhibition of GIP secretion can significantly improve T2DM associated with obesity." (PMID 31214029, 2019). "To avoid overlooking the heritability of obesity traits due to unknown interactions between GIP and GIPR variants, we performed gene–gene interaction (epistasis) analyses." (PMID 28530680, 2017). "Although the mechanisms underlying the anti-obesity effects of WB remains uncertain, the extrapancreatic GIP/GIPR signaling activity may play a significant role in increasing fat oxidation." (PMID 28970776, 2017). "Given that GIPRs are expressed in various tissues, including pancreatic islets, adipocytes, brain and stomach, GIP signaling has been implicated in various activities, which may link overnutrition to obesity, insulin resistance and T2DM." (PMID 28530680, 2017). "Mice in which GIP-action is prevented by knocking out the GIP-receptor, by treatment with a GIP-receptor antagonist or by ablation of GIP-secreting cells, are somewhat protected from developing obesity on a high-fat diet or on the leptin-deficient, hence overeating, ob/ob-background." (PMID 20204054, 2010). "It remains to be shown whether elevated GIP levels seen in these reports drive further fat accumulation or reflect a failing counterregulatory response; deleting GIP in the context of leptin deficiency, however, had little effect on the development of obesity in ob/ob mice." (PMID 40166681, 2025). "Along with the obesity-protecting phenotype seen in Gipr deficient mice, and the diminished insulinotropic action of GIP in people living with T2D [144,], these data initially suggested that GIP may have no pharmacological potential for the treatment of obesity and diabetes." (PMID 40024571, 2025). "However, the exact mechanism underlying the anti-obesity effect of GIP or the GIPR system remains unclear." (PMID 39940910, 2025). "Notably, glucagon-like peptide-1 receptor agonists (GLP-1 RAs), such as semaglutide, liraglutide, and the recently approved dual GLP-1/GIP RAs agonist tirzepatide, have emerged as effective medications for managing obesity, resulting in significant weight loss." (PMID 38715796, 2024).
Obesity (continued). "Moreover, GIP at pharmaceutical doses may prevent atherosclerosis, causing obesity, and the positive benefits of GIP may also be maintained in animals." (PMID 38987789, 2024). "Therefore, deficiency of GIP attenuates the development of ovariectomized-induced obesity in mice." (PMID 37208555, 2023). "Thus, GIP is implicated in obesity-induced IR and the development of T2DM." (PMID 37208555, 2023). "Restraining GIP signals may lead to the reduction of disease risk such as obesity." (PMID 28166771, 2017). "Moreover, to determine whether these associations with GIP variants reflected differences between overall obesity and fat distribution, we repeated our association analysis, including BMI, as a covariate." (PMID 28530680, 2017). "Furthermore, GIP may be directly implicated in fat metabolism and development of obesity by influencing insulin sensitivity of adipocytes." (PMID 22619730, 2012). "Given the established links between GIP, obesity, inflammation, and insulin resistance, our findings reinforce the notion that endogenous GIP plays a relevant role in the metabolic dysregulations associated with increased adiposity." (PMID 41528263, 2026). "Multi-agonist peptides that incorporate AMY receptor agonism have also been developed as illustrated by PTT-A, a long-acting tetra-agonist at the GLP-1, GIP, amylin and calcitonin receptors that decreased food intake and body weight in a rat model of obesity." (PMID 41174263, 2026). "The growing use of glucagon-like peptide-1 (GLP-1) receptor agonists and dual GIP/GLP-1 agonists has intensified debate over the role of pharmacotherapy in addressing obesity." (PMID 41645430, 2026). "Modern glucagon-like peptide 1 (GLP-1) analogues and the combined gastric inhibitory polypeptide (GIP)/GLP‐1 agonist tirzepatide play an important role in the combined treatment of obesity and type 2 diabetes mellitus." (PMID 42162469, 2026). "Some evidence suggests that individuals with overweight/obesity exhibit increased fasting and postprandial GIP secretion following an OGTT or MMT." (PMID 41575482, 2026). "GLP-1/GIP pharmacotherapy should be viewed as a component of an integrated model of obesity treatment." (PMID 42278190, 2026). "Collectively, SUMMIT offers high‐quality evidence that targeting obesity and metabolic dysfunction with a dual GIP/GLP‐1 agonist can modify the disease trajectory in HFpEF, reducing HF events while improving exercise capacity and quality of life." (PMID 41566974, 2026). "Accordingly, a PAR2-mutant mouse resistant to TMPRSS2 cleavage is protected from GIP upregulation and diet-induced obesity." (PMID 41842964, 2026). "Although widespread adoption of GLP-1 and GLP-1/GIP medications has the potential to improve population health by reducing obesity-related diseases, the financial implications are considerable." (PMID 41501776, 2026). "GLP-1 receptor agonists and dual GLP-1/GIP agonists have significantly transformed the treatment of obesity, enabling clinically meaningful weight reduction and improvements in cardiometabolic parameters." (PMID 42278190, 2026). "The development of drugs based on the incretins GLP-1 and GIP has revolutionized the treatment of diabetes and obesity." (PMID 41542598, 2026). "The emergence of incretin-based therapies, particularly GLP-1 (glucagon-like peptide-1) and GIP (glucose-dependent insulinotropic polypeptide) receptor agonists, has transformed the therapeutic landscape for initially type 2 diabetes and now obesity." (PMID 41835241, 2025). "For the drug development industry, developing drugs to prevent muscle wasting and collaborating with the successful obesity management drug GLP-1/GIP agonists is very promising." (PMID 41515907, 2025). "Elevated GIP in obesity, and related observations of GIP effects on adipose tissue, led Vincent Marks in 1988 to describe GIP as ‘The Obesity Hormone’." (PMID 40024571, 2025).